ARHGEF1 (Rho guanine nucleotide exchange factor 1)
Description:
Seems to play a role in the regulation of RhoA GTPase by guanine nucleotide-binding alpha-12 (GNA12) and alpha-13 (GNA13) subunits. Acts as a GTPase-activating protein (GAP) for GNA12 and GNA13, and as guanine nucleotide exchange factor (GEF) for RhoA GTPase. Activated G alpha 13/GNA13 stimulates the RhoGEF activity through interaction with the RGS-like domain. This GEF activity is inhibited by binding to activated GNA12. Mediates angiotensin-2-induced RhoA activation. In lymphoid follicles, may trigger activation of GNA13 as part of S1PR2-dependent signaling pathway that leads to inhibition of germinal center (GC) B cell growth and migration outside the GC niche.
Synonyms: p115-RhoGEF; SUB1.5; LBCL2; GEF1; IMD62; LSC
Tractability: Small molecule: a structure with a bound ligand is known. Antibody: its Gene Ontology location is reachable by antibodies, with high confidence. PROTAC: ubiquitination databases record sites on it; its protein half-life has been measured.
Gene: Protein-coding gene on chromosome 19 (41,883,079 to 41,930,150, forward strand). Ensembl gene ENSG00000076928.
Subcellular location: Cytoplasm; Membrane
Subcellular location (Human Protein Atlas): Cytosol; Plasma membrane
Pathways (Reactome):
Signal Transduction: G alpha (12/13) signalling events; NRAGE signals death through JNK; RHOA GTPase cycle; RHOB GTPase cycle; RHOC GTPase cycle
Gene Ontology:
Molecular function: guanyl-nucleotide exchange factor activity; protein binding; RNA binding; G protein-coupled receptor binding; GTPase activator activity
Biological process: Rho-activating G protein-coupled receptor signaling pathway; G protein-coupled receptor signaling pathway; regulation of small GTPase mediated signal transduction; Rho protein signal transduction
Cellular component: cytosol; plasma membrane; cytoplasm; membrane
Genetic constraint (gnomAD): Loss-of-function variants: 40 observed, 113.51 expected, observed/expected ratio (o/e) 0.35, 90% interval 0.27 to 0.46. The upper end of that interval is the gene's LOEUF score, 0.46, which puts it in group 2 of 6, group 1 being the genes least tolerant of losing a copy. Missense variants: 976 observed, 1,244.3 expected, observed/expected ratio (o/e) 0.78, 90% interval 0.74 to 0.83. Synonymous variants: 494 observed, 502.63 expected, observed/expected ratio (o/e) 0.98, 90% interval 0.91 to 1.06.
Gene-disease validity (ClinGen):
ClinGen rates the evidence that ARHGEF1 causes each of these diseases.
immunodeficiency 62 (autosomal recessive): Limited.
Homologues: Orthologues: chimpanzee ARHGEF1 (99% identical), macaque ARHGEF1 (90% identical), mouse Arhgef1 (88% identical), rat Arhgef1 (88% identical), pig ARHGEF1 (88% identical), dog ARHGEF1 (83% identical), tropical clawed frog arhgef1 (51% identical), zebrafish arhgef1 (41% identical), Caenorhabditis elegans rhgf-1 (27% identical), Drosophila melanogaster RhoGEF2 (20% identical), Drosophila melanogaster cyst (17% identical), Caenorhabditis elegans prhg-1 (13% identical), and 1 more. Paralogues in human: ARHGEF12 (39% identical), ARHGEF11 (35% identical), ARHGEF28 (18% identical), ARHGEF18 (18% identical), ARHGEF2 (16% identical), NET1 (13% identical), PLEKHG6 (12% identical), ARHGEF3 (11% identical).
Diseases named in the same sentence as ARHGEF1 in open-access papers:
ARHGEF1 is named in the same sentence as 45 diseases in open-access papers, as found by Europe PMC text mining. Sharing a sentence is not in itself a finding about the gene and the disease. The quoted sentences say what the papers report.
breast cancer (9 papers, 2015 to 2025). A primary or metastatic malignant neoplasm involving the breast. "Immunoblot analysis of anti-cortactin or anti-ARHGEF1 i.p. by using lysates made from ROR1+ breast-cancer PDX cells revealed that ARHGEF1 associated with cortactin, and more specifically Y421-phosphorylated cortactin." (PMID 31667337, 2019). "Intriguingly, as cells form intercellular contacts, ArhGEF1 is reported to redistribute to cell junctions in breast cancer cells where it stimulates RhoA activation of diaphanous to promote cortical F-actin formation." (PMID 33504879, 2021). "In conclusion, the present study demonstrates a previously unrecognized ROR1/cortactin/ARHGEF1-dependent pathway leading to activation of RhoA in response to Wnt5a in breast-cancer cells." (PMID 31667337, 2019). "We established that the proline at 841 of ROR1 was required for it to recruit cortactin and ARHGEF1, activate RhoA, and enhance breast-cancer-cell migration in vitro or development of metastases in vivo." (PMID 31667337, 2019). "We found several targets of QKI and RBFOX1, including FLNB, SLK, USO1, ENAH, ESYT2, NUMB and ARHGEF1, to be among the most differentially spliced genes in basal B breast cancer cell lines." (PMID 30059005, 2018). "Moreover, TET3 knocked-down cells under normoxia exhibited an identical alternative splicing pattern of ESRP1 targets (hMENA, SLK, SCRIB, RALGPS2, SLC37A2, FNIP1, CD44, and ARHGEF1) as the hypoxic breast cancer cells." (PMID 34362878, 2021). "In this regard, we found that cirmtuzumab could block the capacity of Wnt5a to induce ROR1 to complex and phosphorylate cortactin, recruit ARHGEF1, and activate RhoA, thereby suppressing breast-cancer-cell migration/metastasis." (PMID 31667337, 2019). "Wnt5a also induced ROR1-dependent tyrosine phosphorylation of cortactin (Y421), which recruited ARHGEF1 to activate RhoA and promote breast-cancer-cell migration; such effects could be inhibited by cirmtuzumab, a humanized mAb specific for ROR1." (PMID 31667337, 2019). "Furthermore, ARHGEF1, CFAP65, PDGFRB and CLEC5A were labeled as prognostic marker by the Human Protein Atlas in renal and breast cancer, endometrial cancer, renal and urothelial cancer, and ovarian cancer, respectively." (PMID 34108011, 2021). "We noted that the ARHGEF1 i.p. generated from lysates of breast-cancer PDX treated with cortactin siRNA had less capacity to generate activated RhoA than the ARHGEF1 i.p. of PDX treated with control, nonspecific siRNA." (PMID 31667337, 2019).
Hypertension (8 papers, 2013 to 2025). The presence of chronic increased pressure in the systemic arterial system. "In VSMCs, Ang II induces JAK2, which activates RhoA guanine nucleotide exchange factor I, Arhgef1, which eventually activates RhoA signaling and causes hypertension." (PMID 36324691, 2022). "In VSMCs, stimulation of JAK2 by Ang II leads to activation of RhoA guanine nucleotide exchange factor I, Arhgef1, which, in turn, stimulates RhoA signaling, causing hypertension." (PMID 31703282, 2019). "We specifically chose to examine ARHGEF1 in more detail because it has previously been implicated in AngII-induced hypertension and shown to be tyrosine phosphorylated by Janus kinase-2 (JAK2) in mesenteric artery as an essential step in its activation by AngII." (PMID 28673614, 2017). "The ARHGEFs, including LARG and ARHGEF1, are critical in vasoconstriction and hypertension." (PMID 41020039, 2025). "In contrast, suppression of Arhgef1 reduces Ang II-induced hypertension." (PMID 36324691, 2022). "On the other hand, inactivation of Arhgef1 attenuates Ang II-mediated high blood pressure." (PMID 31703282, 2019). "These insights not only elucidate cardiovascular disease mechanisms but also highlight potential GEF‐targeted therapies (e.g., against VAV3, ARHGEF1, TIAM1, or PDZ‐RhoGEF) for hypertension, atherosclerosis, and myocardial regeneration." (PMID 41020039, 2025). "In cardiovascular diseases, RhoGEFs such as ARHGEF1 and LARG contribute to hypertension and aneurysm formation through activation of the Ang II‐induced RhoA/ROCK pathway, leading to endothelial dysfunction." (PMID 41020039, 2025). "Arhgef1 plays a significant role in Ang II/AT1 receptor-induced RhoA activation in smooth muscle cells, vasoconstriction, and hypertension, and Arhgef1/RhoA signaling is turned on by renin-angiotensin-aldosterone-system (RAAS) activation in humans." (PMID 31174369, 2019). "Furthermore, Jak2‐mediated phosphorylation of ARHGEF1 at Tyr738 activates RhoA, increasing VSMC contractility and vascular resistance—a key mechanism in hypertension." (PMID 41020039, 2025). "They generated a mouse model specifically lacking Arhgef1 in smooth muscle cells (SM-Arhgef1–/–) and demonstrated that SM-Arhgef1–/– mice showed resistance to Ang II-dependent hypertension but did not affect normal BP regulation." (PMID 33803946, 2021).
leukemia (4 papers, 2013 to 2019). A malignant (clonal) hematologic disorder, involving hematopoietic stem cells and characterized by the presence of primitive or atypical myeloid or lymphoid cells in the bone marrow and the blood. "Here we report our studies evaluating whether cortactin is recruited to ROR1 upon stimulation with Wnt5a, undergoes tyrosine phosphorylation, and recruits/activates ARHGEF1 to promote F-actin polymerization and leukemia-cell migration." (PMID 30568170, 2019). "Collectively, these studies reveal that Wnt5a induces ROR1 to complex with cortactin/HS1/ARHGEF1 at P841, which induces phosphorylation of cortactin and HS1, activation of ARHGEF1 and RhoA, thereby enhancing leukemia-cell migration." (PMID 30568170, 2019).
atherosclerosis (3 papers, 2020 to 2025). A disease characterized by the build-up of fatty material and calcium deposition in the arterial wall resulting in partial or complete occlusion of the arterial lumen. "Ang II enhances leukocyte–endothelial adhesion via ARHGEF1, and ARHGEF1‐deficient mice show reduced leukocyte recruitment and atherosclerosis, implicating ARHGEF1 in β2 integrin regulation." (PMID 41020039, 2025). "Arhgef1 activation in leukocytes is causally associated with the development of atherosclerosis." (PMID 35047576, 2021). "Among the reasons for this finding, Arhgef1 was activated, and more leukocytes were recruited to the endothelium to accelerate atherosclerosis." (PMID 35047576, 2021). "ARHGEF1 also contributes to vascular inflammation and atherosclerosis." (PMID 41020039, 2025). "In addition to SGEF, the other Rho GEF protein, RhoA GEF Arhgef1 that is essential for Ang II-induced inflammation, is also a key molecule for atherosclerosis." (PMID 35047576, 2021). "In the mouse model, the deletion of Arhgef1 inhibits Ang II-dependent immune cell activation and their recruitment to the arterial endothelium, which suggests that the Arhgef1 can be a novel target for therapeutic intervention in atherosclerosis." (PMID 33379334, 2020).
liver disease (2 papers, 2015 to 2019). "Another target of miRNA-192 that showed overlap with known pathways of alcoholic hepatitis is Jak2/Arhgef1 signaling pathway, which is correlated with severity of liver disease." (PMID 26264599, 2015).
melanoma (2 papers, 2019 to 2025). A malignant, usually aggressive tumor composed of atypical, neoplastic melanocytes. "This corresponded to a reduction in the frequency of mCherry-labelled tumour cells in the lungs of Arhgef1-deficient mice upon intravenous injection of B78ChOva melanoma cells." (PMID 40044852, 2025). "Confirming the results of our initial screen using littermate controls, we found a reduced number of metastases in the lungs of Arhgef1-deficient mice compared with wild-type controls after intravenous injection of syngeneic B16 melanoma cells." (PMID 40044852, 2025). "Of note, we also checked cBioPortal and found that these proteins related to angiogenesis (i.e. FASN, CLIC4, HSPB1, ARHGEF1, PHGDH, MYO1C, CAV1) are altered in a total of 242 melanoma patients out of a total of 471 (51.36%)." (PMID 31142788, 2019).
emphysema (1 paper, 2012). "This response was measured in both healthy wild type (C57BL/6) mice as well as mouse mutants deficient in the expression of Arhgef1 (Arhgef1−/−) that display constitutive pulmonary inflammation and decreased lung elastance reminiscent of emphysema." (PMID 22934051, 2012).
epilepsy (1 paper, 2025). A brain disorder characterized by episodes of abnormally increased neuronal discharge resulting in transient episodes of sensory or motor neurological dysfunction, or psychic dysfunction. "The VerteBrain dataset uncovers candidate disease mechanisms, including roles for ARHGEF1 in short stature syndromes, synaptic vesicle trafficking complexes in epilepsy, and RELCH in congenital deafness." (PMID 40501792, 2025).
Insulin resistance (1 paper, 2024). Increased resistance towards insulin, that is, diminished effectiveness of insulin in reducing blood glucose levels. "ARHGEF1 plays a significant role in cellular processes such as insulin secretion, insulin signal transduction, and the lipid metabolism, and is associated with type 2 diabetes and insulin resistance." (PMID 39684650, 2024).
metastatic cancers (1 paper, 2021). A carcinoma which has spread from the original site of growth to another anatomic site. "We also identified six genes (KHDRBS2, IQSEC1, ARHGEF1, ARID5A, IRX5, and TMC6) that were activated in metastatic cancers in two of the three cancer types and might be associated with metastatic traits." (PMID 34294701, 2021).
primary immunodeficiencies (1 paper, 2021). "Impaired immune responses have been observed in primary immunodeficiencies associated with disrupted regulation of actin dynamics, such as Wiskott-Aldrich Syndrome (WASP), Coronin1A, Rac2, and ARHGEF1." (PMID 34232960, 2021).
cancer (9 papers, 2008 to 2025). A tumor composed of atypical neoplastic, often pleomorphic cells that invade other tissues. "Here we show that platelet-derived TXA2 functions as a potent immunoregulatory molecule that suppresses T cell immunity to cancer metastasis by inducing the immunosuppressive function of ARHGEF1." (PMID 40044852, 2025). "In this study, we show that platelet TXA2 suppresses immunity to cancer metastasis by activating a T cell-intrinsic immunosuppressive pathway that is dependent on the guanine exchange factor ARHGEF1." (PMID 40044852, 2025). "They observed that in the ROR1+MCF7 cells, Wnt5a stimulated the ROR1-dependent cortactin phosphorylation which recruited ARHGEF1 (Rho guanine nucleotide exchange factor 1) to activate RhoA and promote cancer cell migration." (PMID 36873868, 2023). "Corresponding to augmented adaptive immune responses to metastasis, Arhgef1 deletion reduced the late accumulation of mCherry-labelled cancer cells in the lungs at days 11 and 17 after tumour injection, but did not affect their early accumulation and growth at days 1 and 7 after tumour injection." (PMID 40044852, 2025). "The dysregulation of rho GTPases, including ARHGEF1, are commonly reported in a variety of cancers." (PMID 35456486, 2022). "HeLa cell lysate was also used in the other western blots, with expression of ARHGEF1, ARHGEF11, ARHGEF12, ARHGAP5, ARHGAP24 and ARHGDIA protein reported in this cancer cell line." (PMID 18190708, 2008). "As a result, we have identified a minimal set of control nodes including beta-catenin, MEK, Rho guanine nucleotide exchange factor-1 (P115RhoGEF) and protein phosphatase 2A (PP2A), that are essential for recovering a quiescent phenotype regardless of the cancer progression stage." (PMID 27765040, 2016). "Another subgroup of PPIs presumably perturbed by cancers is characterized by negative or near-zero r-values in cancers and positive r-values of gene co-expression in conditionally normal tissues, for example, C1orf131/EIF3L, C19orf53/APEX1, C1orf198/PPP2R1A and C1orf198/ARHGEF1." (PMID 37373333, 2023).
tumor (5 papers, 2017 to 2025). "Similar to the lack of substantial effect on the growth of primary MMTV-PyMT breast tumours, ARHGEF1 deficiency had minimal effect on the growth of subcutaneously implanted syngeneic MC38 colorectal adenocarcinoma tumours." (PMID 40044852, 2025). "We did not observe major differences in the frequency of mature haematopoietic lineages in tumour-bearing lungs of Arhgef1-deficient mice compared with wild-type controls." (PMID 40044852, 2025). "Moreover, aspirin treatment in vivo resulted in increased capacity for TCR-driven S6 phosphorylation among antigen-experienced CD4+ and CD8+ T cells from tumour-bearing lungs of wild-type mice, to increased levels observed in Arhgef1-deficient mice treated with either aspirin or vehicle control." (PMID 40044852, 2025). "Of note, we observed increased cytokine polyfunctionality and reduced expression of the exhaustion markers PD-1 and TOX among tumour antigen-specific CD8+ T cells responding to ovalbumin (OVA) expressed by B78ChOva metastases in lungs of Arhgef1-cKO mice." (PMID 40044852, 2025). "Mechanistically, our results indicate that the tumor suppressive phenotype elicited upon IER5L targeting is associated to changes in the transcriptional program of proliferation and monomeric G protein regulators such as RCC2 and ARHGEF1." (PMID 39025841, 2024). "Although for many a function in B cells is unknown, for others (namely Arhgef1, Gadd45g, Sh2b3, and Map2k7), tumor-suppressive and/or antiproliferative activity was described." (PMID 32407433, 2020). "The main functions of the top genes in OSPC2 network were associated to sensitization to chemotherapy (CXCR4, ANKRD1, CYR61, EDN1, ATP1B1, ARHGEF1, RTF1), and tumor suppression (FGFR3, BCL11B)." (PMID 28482906, 2017).
bacterial infection (1 paper, 2020). "Functional annotation of putatively selected genes revealed that these genes were predominantly associated with immune-related functions, inclusive of genes such as C5AR1 and MYH10 (bacterial infection); ARHGEF1, ERCC2 and TRAF2 (viral infection) and IFNGR2 (both viral and bacterial infection)." (PMID 33116287, 2020).
ARHGEF1 also shares sentences with these, for which no sentence is quoted: developmental delay (4 papers); Intellectual disability (3); microcephaly (3); autism spectrum disorder (2); Burkitt lymphoma (2); cardiovascular diseases (2); COVID-19 (2); prostate carcinoma (2); acute lymphoblastic leukemia (1); adenocarcinoma (1); adenoma (1); alcoholic hepatitis (1); allergic asthma (1); B cell lymphomas (1); bipolar disorder (1); breast tumor (1); chronic obstructive pulmonary disease (1); diffuse large B-cell lymphoma (1); endometrial cancer (1); infection (1); Kaposi's sarcoma (1); Leukocyte adhesion deficiency type III (1); lymphoma (1); neurodevelopmental disorder (1); ovarian carcinoma (1); portal hypertension (1); prostate tumor (1); pulmonary hypertension (1); schizophrenia (1); type 2 diabetes (1).
A further 1 disease shares a sentence with ARHGEF1 in 1 paper.